IDH3G (isocitrate dehydrogenase (NAD(+)) 3 non-catalytic subunit gamma)
Description:
Regulatory subunit which plays a role in the allosteric regulation of the enzyme catalyzing the decarboxylation of isocitrate (ICT) into alpha-ketoglutarate. The heterodimer composed of the alpha (IDH3A) and beta (IDH3B) subunits and the heterodimer composed of the alpha (IDH3A) and gamma (IDH3G) subunits, have considerable basal activity but the full activity of the heterotetramer (containing two subunits of IDH3A, one of IDH3B and one of IDH3G) requires the assembly and cooperative function of both heterodimers.
Synonyms: H-IDHG; RP99
Tractability: Small molecule: a structure with a bound ligand is known. PROTAC: ubiquitination databases record sites on it; its protein half-life has been measured.
Gene: Protein-coding gene on chromosome X (153,785,735 to 153,794,535, reverse strand). Ensembl gene ENSG00000067829.
Subcellular location: Mitochondrion; Photoreceptor inner segment
Subcellular location (Human Protein Atlas): Mitochondria; Nucleoli; Plasma membrane
Pathways (Reactome):
Metabolism: Citric acid cycle (TCA cycle)
Protein localization: Mitochondrial protein import
Gene Ontology:
Molecular function: magnesium ion binding; protein binding; isocitrate dehydrogenase (NAD+) activity; NAD binding; oxidoreductase activity, acting on the CH-OH group of donors, NAD or NADP as acceptor
Biological process: tricarboxylic acid cycle; carbohydrate metabolic process; isocitrate metabolic process
Cellular component: isocitrate dehydrogenase complex (NAD+); mitochondrion; photoreceptor inner segment; mitochondrial matrix
Homologues: Orthologues: chimpanzee IDH3G (99% identical), dog IDH3G (96% identical), guinea pig IDH3G (96% identical), mouse Idh3g (95% identical), rat Idh3g (94% identical), macaque IDH3G (93% identical), pig IDH3G (82% identical), tropical clawed frog idh3g (78% identical), rabbit IDH3G (75% identical), zebrafish idh3g (70% identical), Caenorhabditis elegans idhg-2 (51% identical), Caenorhabditis elegans idhg-1 (50% identical), and 2 more. Paralogues in human: IDH3B (48% identical), IDH3A (40% identical).
Diseases named in the same sentence as IDH3G in open-access papers:
IDH3G is named in the same sentence as 17 diseases in open-access papers, as found by Europe PMC text mining. Sharing a sentence is not in itself a finding about the gene and the disease. The quoted sentences say what the papers report.
non-small cell lung carcinoma (5 papers, 2022 to 2025). A group of at least three distinct histological types of lung cancer, including non-small cell squamous cell carcinoma, adenocarcinoma, and large cell carcinoma. "Glycolytic enzymes (HK-1, PKM2) demonstrated down-regulation, while TCA cycle enzymes (SDHA, IDH3G) revealed up-regulation in their mRNA expressions in non-small-cell lung cancer during in vitro assays." (PMID 40755753, 2025). "Disturbed lactate metabolism in non-small cell lung cancer (NSCLC) mediates the expression of genes such as HK-1 and IDH3G through histone lactylation, regulating mitochondrial homeostasis as well as cellular metabolism." (PMID 36686771, 2022). "In non-small cell lung cancer (NSCLC) cells, lactate downregulated glycolytic enzymes hexokinase 1 (HK-1) and pyruvate kinase (PKM) while upregulating tricarboxylic acid cycle enzymes succinate dehydrogenase A (SDHA) and isocitrate dehydrogenase 3γ (IDH3G) mRNA levels." (PMID 38812044, 2024).
lung carcinoma (2 papers, 2024). "The malignant progression of lung cancer is driven by the promotion of glycolysis-related lactate production and the lactylation process affecting IDH3G." (PMID 38660376, 2024).
cervical cancer (1 paper, 2009). A primary or metastatic malignant neoplasm involving the cervix. "Many of the genes, including BIRC2, BIRC3, ATF5, NUP62, FASTKD3, IDH3G, and POFUTI, have been found to be regulated by gains or losses in previous cervical cancer studies." (PMID 19911042, 2009).
cognitive decline (1 paper, 2023). "Pearson correlation analysis found that the IDH3G, DLD, SUCLA2, MDH1 showed moderate positive correlations with MMSE scores (r = 0.365–0.441, p < 0.05), suggesting that their expression can effectively track the progression of cognitive decline." (PMID 37575300, 2023).
endometrial cancer (1 paper, 2016). Primary or metastatic malignant neoplasm involving the endometrium (mucous membrane that lines the endometrial cavity). "IDH3G was identified in a module and as a hub gene associated with endometrial cancer, which is consistent with our results." (PMID 26735889, 2016).
esophageal adenocarcinoma (1 paper, 2022). A malignant tumor with glandular differentiation arising predominantly from Barrett mucosa in the lower third of the esophagus. "Similarly, the increased expression of HSPH1, IDH3G, NUDT7 and PDHA1 was associated with shorter OS in the subgroup of patients suffering from esophageal adenocarcinoma (EAD)." (PMID 36298586, 2022).
major depressive disorder (1 paper, 2024). An episode of depression lasting two or more weeks without an intervening episode of mania. "In the TCA cycle, CS, IDH3G, SDHA, and SDHB were upregulated in major depressive disorder and downregulated in ketosis, whereas SUCLG2 was downregulated in both." (PMID 39125835, 2024).
TCA cycle disorders (1 paper, 2025). "Here, we show that impaired expression of IDH3G and MDH2, resulting in reduced α-KG levels and upregulated fumarate levels, is an important manifestation of PD TCA cycle disorders and the metabolic basis for mitochondrial-driven PD pathogenesis." (PMID 40730642, 2025).
tumor (7 papers, 2009 to 2024). "Immunohistochemical staining results for IDH3G that mined from the HPA further confirmed its high expression in GC tumor tissues." (PMID 36229828, 2022). "A number of mitochondrial proteins with relevance to tumour pathophysiology were altered, including BSG, SNCB and three Isocitrate dehydrogenase 3 forms (IDH3A, IDH3B, and IDH3G)." (PMID 24728830, 2014). "Consistent with this premise, tumor cells most sensitive to these agents exhibit over expression of TCA-related discriminating genes, IDH3A, IDH1, IDH3G, ACO2 and ACLY." (PMID 23056181, 2012). "Several proteins, for example BSG (increased in GBM), SNCB (decreased in GBM) and IDH3 (with IDH3A, IDH3G and IDH3B all decreased in GBM), did not fall into an obvious functional grouping but are pertinent to tumour pathophysiology (see “Discussion” section)." (PMID 24728830, 2014).
cancer (3 papers, 2022 to 2025). A tumor composed of atypical neoplastic, often pleomorphic cells that invade other tissues. "In contrast, ENO3, IDH2, IDH3G, and MDH2, genes that encode proteins that generally represses the proliferative, migratory, and invasive capacities of cancer cells, displayed the strongest positive correlations across nearly all cancers." (PMID 40806276, 2025). "The results showed that the expression levels of LDHA, CS, IDH3G were significantly higher in cancer tissues than those in normal tissues." (PMID 36229828, 2022). "Additionally, cancer metabolism-related genes, including PFKM, IDH3G, PYCR1, and BCAT1, were strongly elevated in expression in response to increased LINC00473 levels." (PMID 38512964, 2024).
infection (1 paper, 2014). The state of being infected such as from the introduction of a foreign agent such as serum, vaccine, antigenic substance or organism. "We found that the knock-down of four genes (DNM3, IDH3G, EPS15 and ATP6AP1) significantly inhibits HIV-1 replication, especially at later time-points (from four to seven days post-infection)." (PMID 25496667, 2014).
neurodegenerative disease (1 paper, 2025). A disorder of the central nervous system characterized by gradual and progressive loss of neural tissue and neurologic function. "In particular, IDH3G and MDH2 were severely reduced in the brain of PD patients, which was similar to the expression patterns in the brain of patients with other neurodegenerative diseases." (PMID 40730642, 2025).
IDH3G also shares sentences with these, for which no sentence is quoted: breast carcinoma (1 paper); COVID-19 (1); glioblastoma (1); heart failure (1); liver fibrosis (1).